CAV1 (caveolin 1)
Diseases named in the same sentence as CAV1 in open-access papers (continued):
Sharing a sentence is not in itself a finding about the gene and the disease.
melanoma (continued). "Alternatively, the expression of E-cadherin suppresses the ability of CAV1 to increase migration of melanoma cells in vitro and promote metastasis in vivo." (PMID 32152405, 2020). "We corroborated by western blotting experiments that PTPN14 and CAV1 co-inmunoprecipitated in the presence of E-cadherin in B16F10 melanoma and other cancer cells." (PMID 32152405, 2020). "Previous studies from our laboratory showed that CAV1 enhanced migration and invasion of melanoma, breast, and colorectal cancer cells." (PMID 31484460, 2019). "For instance, TEXs expressing CD63 and caveolin-1 in plasma can perform as non-invasive markers of melanoma, and reflect the clinical management of cancer patients." (PMID 31438991, 2019). "Of note, we also checked cBioPortal and found that these proteins related to angiogenesis (i.e. FASN, CLIC4, HSPB1, ARHGEF1, PHGDH, MYO1C, CAV1) are altered in a total of 242 melanoma patients out of a total of 471 (51.36%)." (PMID 31142788, 2019). "This notion is further supported by a considerable body of evidence suggesting that increased CAV1 favors experimental metastasis of tumor cells of varying origin, including those from prostate, pancreas, bladder, and melanomas." (PMID 31362353, 2019). "Using an ELISA assay to analyze plasma samples, a significantly augmented ratio of exosomes containing tumor markers, including CAV1, was detected in melanoma patients compared to healthy individuals." (PMID 31362353, 2019). "It is possible, that in WM266–4-GnT-III melanoma cells studied here, the level of caveolin-1 is thus too low to localize GnT-III in the early compartments of the secretory pathway." (PMID 29502191, 2018). "Exo isolated from the sera of melanoma patients express higher amounts of CAV-1, S100B, and MIA (melanoma inhibitory activity) than measured in healthy controls." (PMID 29755693, 2018). "Exosomes expressing CD63 and cav1 have been described in large amount in plasma of melanoma patients." (PMID 29760588, 2018). "In melanoma cells, CAV1 expression induces an increase in cell migration and invasion by the activation of Rac1." (PMID 29340103, 2017). "Surprisingly, in another paper of the same group, Capozza and coworkers injected B16F10 cells intradermally and showed that tumor growth of B16F10 melanoma cells increases in Cav-1−/− mice and decreases in Cav-2−/− mice." (PMID 29250058, 2017). "A retrospective study in stage III and IV melanoma patients showed increased levels of caveolin-1- EVs in plasma with a sensitivity of 69% and specificity of 96.3% while levels of serum LDH were altered only in 12.5% of patients." (PMID 26689993, 2016). "In vivo, the expression of CAV1 in B16F10 melanoma cells enhances metastasis to the lungs of C57BL/6 mice." (PMID 27259249, 2016). "Specific ECM-integrin interactions and Y14 phosphorylation are required for CAV1-enhanced melanoma cell migration, invasion and metastasis to the lung." (PMID 27259249, 2016). "Once within the lung matrix rich in the ECM proteins fibronectin and laminin, CAV1 expression in melanoma cells is likely to also favor tissue invasion and colonization (lung colonization)." (PMID 27259249, 2016). "Local cross-talk exists between Cav-1, overexpressed in melanoma, and NOX1, modulating NOX1 activity." (PMID 27756874, 2016). "We have previously determined the importance of CAV1 in promoting lung metastasis using a B16F10 melanoma model in syngeneic C57BL/6 mice and reported that overexpression of CAV1 in B16F10 cells led to increased lung metastasis compared with control cells." (PMID 27259249, 2016). "To assess the relevance of CAV1 in promoting the invasive phenotype of B16F10 melanomas, we evaluated cell behavior in a Matrigel assay." (PMID 27259249, 2016). "Collectively, these results suggest that increased levels of FASN, Cav-1, and P-gp in tumors are associated with increased tumor growth and impairment in the outcome of DTIC therapy in melanoma under obese state." (PMID 27980732, 2016).
melanoma (continued). "In NRAS-ΔPTEN murine melanoma tumours, western blot analysis revealed that the levels of CAV1, β-catenin and ECAD were higher than in NRAS tumours." (PMID 26307673, 2015). "Chavrier, L. Cantley, H. Clevers, N. Leslie and R. Kemler for providing human melanoma cell lines and CAV1-RFP/-GFP, p110 CAAX/KD, TOP-FOP constructs, PTEN mutant constructs and gp84 antibody, respectively." (PMID 26307673, 2015). "Hs944t human melanoma cells were transfected with miR-203 and miR-199a-5p mimics, which led to the reduction of CAV1 mRNA and protein." (PMID 26307673, 2015). "In a related study, subcutaneous injection of B16 melanoma cells in Cav1 KO mice resulted in a reduced tumor growth compared to injection of tumor cells in WT mice." (PMID 26179155, 2015). "In contrast, Cav1 promote proliferation whereas it suppressed migration and invasion of melanoma cells through the inhibition of the integrin/FAK/Src signaling pathway." (PMID 26474461, 2015). "We first verified that CAV1 and β-catenin are able to immuno-complex in a reciprocal manner in Rosi human melanoma and HCT116 human carcinoma cell lines." (PMID 26307673, 2015). "Consistent with this interpretation, the expression of CAV1 was increased in human melanomas in tissues and cell lines compared with melanocytes from patients, as evidenced by western blotting and immunohistochemical analysis." (PMID 24500501, 2014). "In this postsurgery setting, CAV1 presence in B16F10 melanomas favoured metastasis to the lung, although tumour suppression at the initial site was still evident." (PMID 24500501, 2014). "A previous study of exosomes from melanoma patient plasma found that CAV-1 was expressed at higher levels in melanoma patients compared to healthy volunteers." (PMID 25594008, 2014). "We then determined how the augmented presence of CAV1 introduced into human A375 or murine B16F10 melanoma cells promoted metastasis to different organs depending on the model." (PMID 24500501, 2014). "Here, we first evaluated the expression of CAV1 in human melanocytes and melanomas and observed a gradual increase in the expression of this protein with progression of disease." (PMID 24500501, 2014). "Our results using mouse B16F10 and human A375 melanoma cells show that augmented CAV1 protein levels enhance the metastatic potential of these cells." (PMID 24500501, 2014). "Alternatively, knocking down CAV1 expression in a melanoma line that has elevated levels reduced proliferation and tumourigenicity." (PMID 24500501, 2014). "Similar clinical values of decreased stromal Cav-1 levels have also been found in gastric cancer (GC), prostate cancer (PC) and malignant melanoma." (PMID 25202343, 2014). "Then, the consequences of elevating CAV1 expression to levels comparable with those detected in the human melanomas were evaluated in two animal models of experimental metastasis." (PMID 24500501, 2014). "Despite such evidence, another recent report indicates that CAV1 blocks metastasis of malignant melanomas in a murine model." (PMID 24500501, 2014). "CAV1 inhibits metastatic potential in melanomas through suppression of the integrin/Src/FAK signaling pathway in melanoma has been reported." (PMID 25180681, 2014). "We examined expression of the three potential predictive biomarkers (ANXA1, CAV-1 and EphA2) in melanoma specimens by IHC." (PMID 25594008, 2014). "It should be noted that at the time of surgery, tumours formed by CAV1-expressing melanoma cells were of essentially the same size as those formed by B16F10 (mock) cells (compare Fig. 4c1 and c2)." (PMID 24500501, 2014). "In an earlier study, we have reported a positive correlation between Cav-1 levels to rapid progression of melanoma in mice fed with high fat diet." (PMID 25178635, 2014). "CAV-1 was expressed in 54/122 (44 %) of melanoma samples, 39/82 (48 %) of primary and 15/40 (38 %) of metastatic melanoma samples." (PMID 25594008, 2014).
melanoma (continued). "Taken together, these results show that progression of melanoma development in humans correlates with increased CAV1 expression." (PMID 24500501, 2014). "CAV1 expression in human melanocytes and melanomas increases with disease progression and is highest in metastatic melanomas." (PMID 24500501, 2014). "We examined expression of SRC kinase and the 3 potential predictive biomarkers, ANXA1, CAV-1 and EphA2, in a cohort of 125 melanoma specimens." (PMID 25594008, 2014). "Together, these studies identified CAV1 as a protein whose expression increases with human melanoma progression and as a factor that favours lung metastasis in preclinical murine postsurgery settings." (PMID 24500501, 2014). "Moderate/strong expression of all three markers (ANXA1, CAV-1 and EphA2) was found in 21/113 (19 %) of the melanoma samples, 16/77 (21 %) of primary melanoma samples and 5/36 (14 %) of metastatic samples." (PMID 25594008, 2014). "Using this model, we provide direct experimental evidence that CAV1 expression in melanomas before surgery favours metastasis and hence represents a negative prognostic marker for the outcome of surgical procedures." (PMID 24500501, 2014). "The effect of increased CAV1 expression can then be evaluated using B16F10 murine melanoma cells injected into syngenic immunocompetent C57BL/6 mice or human A375 melanoma cells injected into immunodeficient B6Rag1−/− mice." (PMID 24500501, 2014). "Here, we show first that CAV1 expression increased as human melanocytes progressed through the different stages to metastatic melanomas." (PMID 24500501, 2014). "Reduced stromal Cav1 expression has also been reported to label a subgroup of patients that have an unfavourable survival prognosis and aggressive malignant melanoma metastases." (PMID 23521716, 2013). "Authors observed that a significant increase in exosomes expressing tumour markers such as Cav1 can be observed in the plasma of melanoma patients with respect to healthy individuals." (PMID 23521716, 2013). "Recently, Cav1 has been reported to reduce metastatic potential in melanoma cells through the suppression of the Integrin/Src/FAK signalling pathway." (PMID 23521716, 2013). "Recently, it has been reported that FASN and Cav-1 interact together and modulate each other in melanoma cells." (PMID 23613870, 2013). "They further determined that the number of caveolin-1 positive plasma exosomes was significantly greater than the number of CD63 positive exosomes in melanoma patients." (PMID 23056502, 2012). "Consistent with the Lin’s study using LLC, increased tumor growth, angiogenesis and tumor vessel permeability were observed in Cav-1 KO mice subcutaneously implanted with B16 melanoma cells." (PMID 26605130, 2012). "Using this assay, we observed that significantly increased amounts of exosomes expressing tumor markers such as caveolin-1 are present in plasma from melanoma patients with respect to healthy individuals." (PMID 19381331, 2009). "Consistently, plasma exosomes expressing CD63 (504±315) or caveolin-1 (619±310) were significantly increased in melanoma patients as compared to healthy donors (223±125 and 228±102, respectively)." (PMID 19381331, 2009). "We evaluated the levels of plasma exosomes expressing CD63 and caveolin-1 in melanoma patients (n = 90) and healthy donors (n = 58)." (PMID 19381331, 2009). "Proteomic analyses of EVs from various melanoma cell lines have revealed that their protein composition varies with the aggressiveness of the parental cells, with Cav1 levels in EVs specifically correlating with the metastatic potential of the corresponding cell lines." (PMID 40963741, 2025). "The study noted that numerous clinical samples may include a high number of exosomal proteins that are specific to melanoma, such as caveolin-1." (PMID 40612948, 2025).
melanoma (continued). "Taken together, these findings indicate that CAV1 acts as a context-dependent regulator in ocular tumors: it is reduced in RB and less aggressive melanomas, but induced in epithelioid melanoma, reflecting its dual roles in tumor suppression and metastasis promotion." (PMID 41374987, 2025). "The palmitoylation of Cav-1 may be a crucial mechanism for its stabilization at the protein level in melanoma cells." (PMID 38921444, 2024). "In summary, exposure of both mouse and human melanoma cells expressing CAV1 together with E-cad overrides the tumor suppressor effect of this complex to enhance migration, invasion, and metastasis to levels comparable to those seen for cells expressing CAV1 in the absence of E-cad." (PMID 38069269, 2023). "Furthermore, the TCGA melanoma database analysis identified a prognostic signature containing CAV1 (caveolin 1), CD36 and CPT1C (carnitine palmitoyltransferase 1C), members of which are responsible for fatty acid uptake and metabolism." (PMID 35628196, 2022). "Finally, the glycolysis inhibitor 2-deoxy-D-glucose reduced CAV1-enhanced migration in vitro and metastasis in vivo of murine melanoma cells." (PMID 35740528, 2022). "Our group has also identified such a reciprocal modulating mechanism in melanoma cells between caveolin-1, a major regulator of signaling platforms and dopachrometautomerase, a melanoma antigen with multiple functions, including melanoma resistance to therapeutical and environmental stress." (PMID 35011682, 2021). "Dysregulation of Cav1 expression in the human skin is associated with hyperproliferative diseases such as melanoma and non-melanoma cancers as well as psoriasis." (PMID 32532976, 2020). "For example, hypoxia could induce Cav-1 protein levels in a HIF1α-dependent manner in murine melanoma and colon-adenocarcinoma cells." (PMID 32528105, 2020). "Furthermore, the involvement of CAFs in melanoma dissemination is confirmed by study analyzing the clinical importance of Cav-1 expression in CM." (PMID 32528879, 2020). "Comparing our previous microarray data (GSE42876 and GSE61671) with the result of current proteomic analysis, the positive and strong correlation that both ANPEP and CAV1 gene products were downregulated in suspended melanoma cells and reattached melanoma cells." (PMID 32756007, 2020). "Notably, CAV1 was also detected together with other tumor markers in exosomes from plasma samples obtained from melanoma patients." (PMID 32458269, 2020). "Furthermore, CAV1 and E-cadherin co-expression also reduce survivin expression and enhance apoptosis in human melanoma cells." (PMID 32152405, 2020). "Moreover, addition of a polyclonal CAV1-specific antibody to the CM from human melanoma cell lines reduced cell migration and invasion." (PMID 31362353, 2019). "Intriguingly, metastasis to the lung following intravenous injection of cells into the tail vein was increased by CAV1 expression alone, while co-expression with E-cadherin ablated the ability of CAV1 to enhance melanoma migration in vitro and metastasis in vivo." (PMID 31362353, 2019). "Similar observations have also been made for CAV1 expression during the development of melanoma." (PMID 31362353, 2019). "Taken together these data indicate that secreted CAV1 promotes invasion of melanoma cell lines." (PMID 31362353, 2019). "Indeed, we observed here that CAV1-enhanced transendothelial migration of melanoma cells is blocked by CGP42112 treatment." (PMID 31484460, 2019). "Interestingly, CAV1 was detected in the conditioned media (CM) of human melanoma cells expressing this protein." (PMID 31362353, 2019). "Finally, AT2R activation was also shown to block CAV1-enhanced melanoma metastasis in a preclinical animal model." (PMID 31484460, 2019). "CAV1 has been suggested to promote melanoma metastasis by enhancing extravasation." (PMID 31484460, 2019). "Additionally, AT2R activation reduced transendothelial migration of A375 human melanoma cells expressing CAV1." (PMID 31484460, 2019).
melanoma (continued). "To get insights into the role of leptin and resistin in causing attenuation in the response to DTIC, we intended to analyze the status of FASN and Cav-1 which are upregulated in melanoma in the obese (HFD) mice, and are known to be involved in resistance to cancer chemotherapy." (PMID 29568521, 2018). "We first evaluated the relative levels of GM1 and Cav-1 in Me665 melanoma cells and CHO cells." (PMID 29783743, 2018). "In the cancers of prostate, colon, lung, melanoma, and Ewing sarcoma, CAV1 has been shown to activate the RAS-ERK-MEK signalling and promote cancer progression, demonstrating that in certain cancer tissue the role of CAV1 in this pathway is opposite as compared to mesothelial cells." (PMID 29402961, 2018). "CD63+ and caveolin-1+ are mutually related, and in conjunction with other biomarkers, such as p-Met, TYRP2, HSP70, HSC70, and VLA-4, this association increases the predictive accuracy of early diagnosis and prognosis of melanoma." (PMID 28659795, 2017). "Although it is known that laminin-induced Cav1 phosphorylation occurs in melanoma cells, and is a central regulator of cell migration, it is unclear as to whether the same happens in astrocytes." (PMID 29326556, 2017). "For other types of cancer, the number of exosomes expressing CD63+ and/or caveolin-1+ are significantly increased in the plasma of patients with melanoma compared to that in healthy individuals, a finding that exhibits a higher detection sensitivity than that of conventional biomarkers." (PMID 28659795, 2017). "Also the tetraspanin CD63, a well known marker of microvesicles, was associated with prometastatic pathways and evidenced together with Cav1 on plasma EXOs of melanoma patients." (PMID 26912358, 2016). "Therefore, it is likely that FASN, Cav-1, and P-gp are cumulatively responsible for impairment in the outcome of chemotherapy in melanoma." (PMID 27980732, 2016). "Related caveolin-1 levels in serum of melanoma patients were found to be of clinical significance." (PMID 27756874, 2016). "Another study, which focused on the size of the primary tumors opposed to metastasis, reported that intradermal coinjection of nude mice with B16F10 melanoma cells and Cav1 KO neonatal dermal fibroblasts increased primary tumor growth when compared to coinjection of tumor cells with WT fibroblasts." (PMID 26179155, 2015). "Our study was limited to the PTEN loss-mediated bypass of OIS on the NRASQ61K background, but the PTEN/CAV1/β-catenin/p16INK4A pathway may hold true in BRAFV600E melanomas as well." (PMID 26307673, 2015). "However, with cancer advanced progression, Cav-1 re-expression was observed in various cancers including breast, lung, prostate, liver, ovarian, pancreas, melanoma, thyroid, colorectal, gastric, renal and pleomorphic malignancies." (PMID 26431273, 2015). "Be as it may, our studies indicate that CAV1 and CAV1-related pathways may be a potential therapeutic target for melanoma treatment." (PMID 26307673, 2015). "PTEN and CAV1 were expressed in 40 and 10 melanomas, respectively." (PMID 26307673, 2015). "Whereas melanoma cell lines clearly demonstrated the causal relationship between PTEN, CAV1, β-catenin and p16INK4A expression to robustly bypass senescence, immunohistochemical studies of melanoma tissue revealed that this mechanism plays a role in only a fraction of cases." (PMID 26307673, 2015). "In addition, we validated this CAV1/PTEN interaction in WM852 and WM793 human melanoma cell lines after immune-precipitation with CAV1." (PMID 26307673, 2015). "Here, two models were used to evaluate how CAV1 expression affects melanoma behaviours in vivo." (PMID 24500501, 2014). "However, a report by Trimmer and colleagues suggested that CAV1 expression is reduced in human metastatic melanoma cell lines and blocks metastasis of malignant melanomas." (PMID 24500501, 2014).